TIALD (transcript inducer of AURKA lysosomal degradation)
Synonyms: AC079360.1
Gene: Long non-coding RNA gene on chromosome 12 (121,856,253 to 121,881,238, forward strand). Ensembl gene ENSG00000256811.
Diseases named in the same sentence as TIALD in open-access papers:
TIALD is named in the same sentence as 4 diseases in open-access papers, as found by Europe PMC text mining. Sharing a sentence is not in itself a finding about the gene and the disease. The quoted sentences say what the papers report.
hepatoma (1 paper, 2023). "Next, we examined the expressions of TIALD in seven human hepatoma cell lines and a normal liver cell line, LO2." (PMID 37773181, 2023).
liver cancer (1 paper, 2023). An epithelial or non-epithelial malignant neoplasm that arises from the liver. "AURKA’s specific inhibitor alisertib exerts effective therapeutic effect on liver cancer with low TIALD expression, which might provide a new insight into HCC therapy." (PMID 37773181, 2023).
cancer (1 paper, 2023). A tumor composed of atypical neoplastic, often pleomorphic cells that invade other tissues. "EMT is well known to be involved in the invasion and metastasis of cancer cells, we next investigated whether TIALD is involved in the regulation of EMT in HCC." (PMID 37773181, 2023). "Our findings expand our understanding of the AURKA degradation pathway, and provides a new theoretical basis for the cancer therapy targeting AURKA, but more studies are needed on how TIALD directs its targeting to lysosomes by binding to AURKA." (PMID 37773181, 2023).
tumor (1 paper, 2023). "Among these lncRNAs, the AC079360.1 (TIALD) was identified to be down-regulated in HCC tissues compared with that in their paired adjacent non-tumor tissues." (PMID 37773181, 2023). "The results showed that TIALD was significantly down-regulated in HCC tissues compared with that in non-tumor tissues." (PMID 37773181, 2023). "Given the important role of AURKA in tumor progression, we speculate that TIALD exerts the function of inhibiting metastasis via binding to AURKA." (PMID 37773181, 2023). "Subsequently, the expression of TIALD was further investigated in an enlarged sample cohort including 110 pairs of HCC and their adjacent non-tumor tissues." (PMID 37773181, 2023).